SNORD116-14 (small nucleolar RNA, C/D box 116-14)
Synonyms: HBII-85-14
Gene: Small nucleolar RNA gene on chromosome 15 (25,080,142 to 25,080,233, forward strand). Ensembl gene ENSG00000206621.
Gene Ontology:
Biological process: RNA processing
Cellular component: nucleolus
Homologues: Orthologues: chimpanzee SNORD116 (100% identical), macaque SNORD116 (99% identical), guinea pig SNORD116 (91% identical), guinea pig SNORD116 (87% identical). Paralogues in human: SNORD116-17 (99% identical), SNORD116-19 (99% identical), SNORD116-15 (98% identical), SNORD116-18 (98% identical), SNORD116-20 (98% identical), SNORD116-21 (98% identical), SNORD116-22 (98% identical), SNORD116-16 (96% identical), SNORD116-12 (92% identical), SNORD116-23 (92% identical), SNORD116-24 (92% identical), SNORD116-2 (90% identical), and 20 more.